DDX19A (DEAD-box helicase 19A)
Description:
ATP-dependent RNA helicase involved in mRNA export from the nucleus. Rather than unwinding RNA duplexes, DDX19 functions as a remodeler of ribonucleoprotein particles, whereby proteins bound to nuclear mRNA are dissociated and replaced by cytoplasmic mRNA binding proteins.
Synonyms: DDX19L; FLJ11126; DDX19-DDX19L
Tractability: PROTAC: UniProt records ubiquitination sites on it; ubiquitination databases record sites on it; its protein half-life has been measured.
Gene: Protein-coding gene on chromosome 16 (70,346,861 to 70,373,992, forward strand). Ensembl gene ENSG00000168872.
Subcellular location: Cytoplasm; Nucleus, nucleoplasm
Subcellular location (Human Protein Atlas): Nucleoplasm
Gene Ontology:
Molecular function: protein binding; ATP hydrolysis activity; ATP binding; nucleic acid binding; RNA helicase activity
Biological process: positive regulation of apoptotic process; response to zinc ion
Cellular component: membrane; cytoplasm; cytoplasmic stress granule; nucleoplasm
Genetic constraint (gnomAD): Loss-of-function variants: 10 observed, 47.12 expected, observed/expected ratio (o/e) 0.21, 90% interval 0.13 to 0.36. The upper end of that interval is the gene's LOEUF score, 0.36, which puts it in group 1 of 6, group 1 being the genes least tolerant of losing a copy. Missense variants: 260 observed, 522.78 expected, observed/expected ratio (o/e) 0.5, 90% interval 0.45 to 0.55. Synonymous variants: 191 observed, 195.71 expected, observed/expected ratio (o/e) 0.98, 90% interval 0.87 to 1.1.
Homologues: Orthologues: mouse Ddx19a (97% identical), rat Ddx19b (97% identical), pig DDX19A (97% identical), rabbit DDX19A (94% identical), zebrafish ddx19b (86% identical), tropical clawed frog ddx19b (85% identical), macaque DDX19A (82% identical), zebrafish ddx19a (79% identical), chimpanzee DDX19A (77% identical). Paralogues in human: DDX19B (96% identical), DDX25 (64% identical), EIF4A1 (32% identical), EIF4A2 (31% identical), EIF4A3 (31% identical), DDX6 (27% identical), DDX4 (27% identical), DDX20 (27% identical), DDX39B (26% identical), DDX3X (26% identical), DDX1 (26% identical), DDX27 (26% identical), and 26 more.
Diseases named in the same sentence as DDX19A in open-access papers:
DDX19A is named in the same sentence as 11 diseases in open-access papers, as found by Europe PMC text mining. Sharing a sentence is not in itself a finding about the gene and the disease. The quoted sentences say what the papers report.
cervical squamous cell carcinoma (5 papers, 2021 to 2025). A squamous cell carcinoma arising from the cervical epithelium. "Previous research revealed that DDX19A was highly expressed in cervical squamous cell carcinoma and promoted cell metastasis by inducing NOX1-mediated reactive oxygen species production, indicating that DDX19A had a cancer-promoting effect." (PMID 39097730, 2024). "A previous study has shown that DDX19A is overexpressed in cervical squamous cell carcinoma and promotes cell invasion and migration by inducing productions of reactive oxygen species." (PMID 34612147, 2021). "DEAD-box RNA helicase 19 A (DDX19A) is overexpressed in cervical squamous cell carcinoma." (PMID 39097730, 2024). "Recent studies have demonstrated that overexpression of DEAD-box helicase 19A (DDX19A) enhances NOX1-mediated ROS production, promoting migration and invasion of cervical squamous cell carcinoma cells." (PMID 40427384, 2025). "Recently, overexpression of DEAD-box helicase 19A (DDX19A) was reported to increase NOX-1-mediated production of reactive oxygen species (ROS) to induce migration and invasion of cervical squamous cell carcinoma cells." (PMID 37679792, 2023).
breast carcinoma (2 papers, 2021). "DDX19A is identified as a prognostic factor of breast cancer disease progression." (PMID 34612147, 2021). "Moreover, a meta-analysis showed that a downsized four-gene signature, consisting of DDX19A, FOXM1, KPNA4, and H2AFV, represents a highly significant finding for the biology underlying histological grades in breast cancer, in particular, regarding cell proliferation, and DNA stability." (PMID 33968728, 2021).
cervical cancer (2 papers, 2021 to 2024). A primary or metastatic malignant neoplasm involving the cervix. "DDX19A is a tumor promoter in cervical cancer; however, its clinical significance and function in GC remain unclear." (PMID 39097730, 2024).
gastric cancer (1 paper, 2024). A primary or metastatic malignant neoplasm involving the stomach. "DDX19A was highly expressed in gastric cancer and positively associated with malignant clinicopathological features and poor prognosis." (PMID 39097730, 2024). "The expression of DDX19A in gastric cancer and paracancerous tissues was evaluated through quantitative polymerase chain reaction, western blotting, and immunohistochemical staining." (PMID 39097730, 2024). "Additionally, DDX19A promoted gastric cancer cell proliferation, migration, and epithelial–mesenchymal transition phenotypes." (PMID 39097730, 2024).
HIV-1 infection (1 paper, 2022). The type species of lentivirus and the etiologic agent of acquired immunodeficiency syndrome (AIDS). "Although a defined function for DDX19 in HIV-1 infection has not yet been reported, DDX19A was co-purified with the HIV-1 pre-integration complex, indicating that it may have an as of yet uncharacterised function in the early stages of HIV-1 viral replication." (PMID 35769258, 2022).
lymph node metastasis (1 paper, 2024). "DDX19A expression positively correlated with tumor grade, depth of invasion, lymph node metastasis, and TNM stage, but not with other clinicopathological features (patient age and sex, tumor size)." (PMID 39097730, 2024).
ovarian carcinoma (1 paper, 2024). A malignant neoplasm originating from the surface ovarian epithelium. "However, another study reported low DDX19A expression in ovarian cancer tissues, indicating that DDX19A exerts an antitumor effect." (PMID 39097730, 2024).
viral infection (1 paper, 2016). "This apparent contradiction with the fact that upon depletion, both DDX19A and DDX19B appear to play a role in viral infection, is likely due to a high expression level of the recombinant DDX19B protein." (PMID 27653209, 2016).
cancer (3 papers, 2014 to 2024). A tumor composed of atypical neoplastic, often pleomorphic cells that invade other tissues. "DDX19A in 184 GC tissues and 156 adjacent non-cancer tissues were detected by IHC, and DDX19A was significantly upregulated in GC tissues when compared to adjacent tissues." (PMID 39097730, 2024). "In conclusion, we identified DDX19A as a novel oncogenic biomarker and promising therapeutic target in patients with GC, which may contribute to exploring the biological function of DDX19A in cancer." (PMID 39097730, 2024). "It is possible that DDX19A has a role in the unwinding of microRNAs duplex during the miRNA maturation process, as the DEAD-protein, ATP-dependent RNA helicase p68 has a role in let-7 microRNA pathway maturation, in cancer cell proliferation and metastasis." (PMID 24866763, 2014). "However, the expression and function of DDX19A in cancer have not been reported." (PMID 33968728, 2021).
tumor (2 papers, 2021 to 2024). "Intriguingly, high expression of DDX19A was associated with lymph node metastasis and larger tumor size." (PMID 33968728, 2021). "To determine whether DDX19A affects GC cell growth in vivo, we established a tumor xenograft model by subcutaneously injecting mice with DDX19A knockdown MGC-803 cells." (PMID 39097730, 2024). "We further investigated whether DDX19A could affect tumor metastasis in vivo." (PMID 33968728, 2021). "In summary, these data indicate that DDX19A may play a tumor-promoting role in CSCC." (PMID 33968728, 2021). "We investigated the molecular mechanism through which DDX19A acts as a tumor driver in GC and identified the PI3K/AKT pathway as a downstream target of DDX19A in GC." (PMID 39097730, 2024). "In this study, data from public databases and the results obtained from our clinical specimens consistently showed increased expression of DDX19A in CSCC, suggesting a tumor-promoting role in CSCC." (PMID 33968728, 2021).
bacterial infection (1 paper, 2024). "Unlike DHX29 or DDX19A, which act as viral RNA sensors and activators of inflammation through the NF-κB or NLRP3 pathways, DDX5 regulates the m6A modification of TLR2/4 mRNA to suppress inflammatory responses pathway during bacterial infection." (PMID 38182816, 2024).